IL4 (interleukin 4)
Diseases named in the same sentence as IL4 in open-access papers (continued):
Sharing a sentence is not in itself a finding about the gene and the disease.
colitis (continued). "Unlike, in B. vulgatus mpk mono-colonized mice which do not develop colitis we observed neither IFN-γ or IL-17 nor IL-10 or IL-4 expression indicating that semi-mature LP DC did not lead to T-cell polarization." (PMID 18545662, 2008). "Many studies have shown that CB or AKK can play a protective role in mouse colitis by regulating some key components related to the inflammatory response, such as pro-inflammatory cytokines (IL-1β, IL-6, and TNF-α) and anti-inflammatory cytokines (IL-4 and IL-10)." (PMID 39840995, 2025). "The frequency of CD4+IL-4+ Th2 cells was mildly reduced after induction of colitis by DSS, which did not change with or without cADSC administration (control: 3.0% ± 0.1%; PBS: 2.3% ± 0.6%; primary: 2.1% ± 2.2%; cADSC-K4DT: 2.2% ± 0.2%; cADSC-K4D: 2.7% ± 1.1%)." (PMID 38139314, 2023). "However, IL-4 depletion did affect Type 1 responses, but did not induce inflammation in the colon or clinical signs of colitis in these mice." (PMID 35442154, 2022). "Moreover, cholecystectomy also reduced mRNA levels of pro-inflammatory cytokines (Il1β, Il6, Tnfα); while it did not affect anti-inflammatory cytokines (Il4, Il10) in colonic tissues under colitis status." (PMID 36050867, 2022). "Since it has been demonstrated that IL9-producing iNKT cells provide protective effects against DSS colitis in an IL4-dependent manner, we decided to examine whether this subset of iNKT cells cooperates with IL22-producing ILC3s in regulating colitis in Yeti mice." (PMID 33513946, 2021). "Furthermore, while experimental colitis upregulated inflammatory genes in the colon, including Tnfa, Il6 and Ifng, UC patients also upregulated IL17A and IL10, followed by a slight increase in IL4 and mevalonate kinase (MVK) expression." (PMID 34434187, 2021). "In accordance with these findings, it was recently shown that soluble mediators from human M(IL4)s stimulated epithelial (i.e. monolayers of the human colon-derived T84 cell line) wound repair in an in vitro assay and, that these cells inhibited DNBS-induced colitis in rag1-/- mice." (PMID 34691050, 2021). "In TNBS-induced colitis, cytokine imbalance was demonstrated by high expression of proinflammatory cytokines (TNF-α, IFN-γ, IL-1β, and IL-17) and low expression of anti-inflammatory cytokines (IL-4 and IL-10) to induce inflammatory damage to the colonic mucosa." (PMID 30894816, 2019). "However, adoptive transfer of IL-4-induced AADC had no impact on the outcome of DNBS-induced colitis." (PMID 28094779, 2017). "Consistent with a previous study showing the restriction of TH1 responses in experimental murine colitis due to basophil-derived IL-4 and IL-642, we could not detect IFN-γ production in vitro co-culture (data not shown)." (PMID 28134325, 2017). "This DSS colitis switches from a Th1-Th17-mediated acute inflammation with increased levels of TNF-α, IL-6 and IL-17, to a predominant Th2-mediated inflammatory response that shows a decrease in TNF-α, IL-6 and IL-17 while increasing levels of anti-inflammatory cytokines IL-4 and IL-10." (PMID 25106058, 2014). "The cytokine profile and histopathology of murine DSS-colitis has similarities with both forms of IBD, namely elevation of pro-inflammatory cytokines, such as TNFα and IFNγ, transmural inflammation, and aphthous erosions (like CD) as well as increased levels of IL-4 and crypt abscesses (like UC)." (PMID 23468885, 2013). "However, since the cKO mice are potent IL-4 producers, and IL-4 mediated inflammation can also lead to colon inflammation, it was not clear whether the increased neutrophils in the colons was driven by an increase in Th17 cells in these mice." (PMID 28051111, 2017). "However, the acute DSS-induced colitis was exacerbated in IL4+/+mice, and not in IL4−/− mice." (PMID 24314293, 2013).
colitis (continued). "Within the context of helminth-therapy for colitis, we noted increased expression of colonic FIZZ1 and arginase-1 mRNA, markers indicative of an M(IL4); however, these markers are not exclusive to M(IL4)s." (PMID 34691050, 2021). "Despite the observed induction of Th1 and Th2 cytokines, only neutralization of IL-4, but not IFN-y, was able to abrogate the development of colitis, suggesting the observed intestinal inflammation to be Th2-dependent." (PMID 31174293, 2019). "In the present study we found that DSS-induced colitis was not exacerbated in immune milk-fed mice, although IFN-γ production increased in LP, but IL-17A and IL-4 productions decreased." (PMID 24686517, 2014). "Mice with colitis, regardless of diet, presented higher concentrations of all measured cytokines (TNF, IL-6, IL-4, IL-10, IFNy), and MCP-1/CCL2." (PMID 22073943, 2011).
breast carcinoma (215 papers, 2003 to 2026). "Clinical studies in patients with breast cancer before chemotherapy have reported that higher circulating levels of IL-4 and IL-10 are associated with better cognitive performance, particularly in attention and processing speed tasks." (PMID 41155372, 2025). "This is in line with data that we published previously showing that IL4-regulated metastatic colonization in mouse models of breast cancer was linked to increased Akt signaling, and IL4-enhanced colony formation in vitro was attenuated by Akt inhibition." (PMID 38731867, 2024). "We then consolidated an OPN pathway and upregulated gene signatures from our findings (Spp1, Timp3, Col11a1, Mmp9, Mmp2, Fn1, Cd44, and Il-4) to interrogate how their predicted activity is associated with relapse-free survival in breast cancer patients." (PMID 39448577, 2024). "Interleukin-1β (IL-1β), vascular endothelial growth factor (VEGF), and IL-4 serum levels and new genetic mutations in breast cancer (BC) patients were assessed in the current study." (PMID 36619680, 2023). "IL-4 signaling was identified to trigger tumor-associated macrophages and enhance invasion in breast cancer." (PMID 38201482, 2023). "The percentages of IL-17- and IL-4-producing CD8+ T cells showed positive association with breast cancer progression and also down-regulation of IFN-γ in these cells was associated with metastasis to the draining LNs." (PMID 36376825, 2022). "In a spontaneous breast cancer model of mice (PyMT) deficient in IL-4, IL-4 was shown to support vessel remodeling." (PMID 35626056, 2022). "Many epidemiologic studies have reported the association of IL-4 gene SNPs with cancer risks, such as breast cancer, gastric cancer, and lung cancer." (PMID 36034203, 2022). "IL4 signaling in macrophages also transcriptionally regulated other genes causally associated with mammary cancer lung metastasis, including Ccl2, Csf1, Ccr1, Hgf and Flt1." (PMID 36077870, 2022). "IL-4-expressing CD4+ T cells were previously shown to promote pulmonary metastasis of breast cancer by directly acting on tumor-associated macrophages, which enhance metastasis through activating epidermal growth factor receptor signaling in cancer cells." (PMID 34707103, 2021). "In breast cancer, upregulation of IL‐4/IL‐4R signaling has been associated with poor prognosis in both human and murine models." (PMID 33682324, 2021). "Next, focusing on data from the entire cohort of patients with breast cancer, we found that high coexpression of IL-31Ra, IL-4, IL-2, and Granzyme B was associated with increased survival, with results almost reaching statistical significance (p=0.056)." (PMID 32843492, 2020). "They verified that promotion of tumor cell survival and proliferation by IL4 involved an increase in glucose uptake and lactate production by murine 4T1 breast cancer cells, associated with an increase in GLUT1 expression, both in vivo and in vitro." (PMID 31936350, 2020). "In breast cancer, IL-4 was reported to be associated with progression, invasion and tumor growth by downregulating MAPK pathway." (PMID 31751357, 2019). "In contrast, elevated IL-4 levels were linked to better response speed and fewer cognitive complaints in patients with breast cancer, suggesting that maintenance of IL-4 levels during cancer care is likely to be neuroprotective." (PMID 28377717, 2017). "The metastatic mouse mammary carcinoma cell line AC2M2 was transduced with control or IL-4 encoding retroviruses and employed in orthotopic engraftment models." (PMID 27563494, 2015). "On the other hand, we and others have reported that IL-4 can inhibit the proliferation of human renal, colon, and breast cancer cells and it can cause regression of certain tumor xenografts in a mouse model of cancer." (PMID 25208941, 2014). "In murine breast cancer models, IL-4 secretion by CD4+ Th2 cells activate tumor-associated macrophages (TAM) to facilitate pulmonary metastasis mediated by secretion of EGF." (PMID 25208941, 2014).
breast carcinoma (continued). "Among these functional states, M2 macrophages activated by IL-4 have been associated with breast cancer invasion, metastasis and poor patient prognosis." (PMID 21939504, 2011). "IL-4 has recently been implicated in the resistance to cell death observed in epithelial tumours, including breast cancer." (PMID 19642980, 2009). "In another study, authors suggested that the increased circulating IL-4 may be influenced by hormone receptor status and might be linked to poorer outcomes in breast cancer." (PMID 41150099, 2025). "In addition, IL‐4 is a pleiotropic cytokine that has been associated with proliferation, metastasis, migration, and invasion of breast cancer cells in several studies." (PMID 38886335, 2024). "IL4-driven polarization of macrophages has been associated with immunosuppression in breast cancer." (PMID 38731867, 2024). "As well as being a risk factor for breast cancer patients, DeNardo DG found that in murine breast cancer models, IL-4 produced by tumor infiltrating CD4 + T cells stimulate M1 to M2 transition of TAMs (Tumor-associated macrophages), thus supporting lung metastasis of breast cancer cells." (PMID 37007080, 2023). "In addition to its essential role in polarization of TSLP-stimulated CD4+ T cells, we find that baseline IL-4/13 signaling, which is also implicated in normal mammary gland development, can protect against breast cancer development." (PMID 35657353, 2022). "Furthermore, IL4 signaling in macrophages regulated the transcript abundance of several other genes already causally associated with mammary cancer lung metastasis including Ccl2, Csf1, Ccr1, Hgf and Flt1." (PMID 36077870, 2022). "Also, the level of ALCAM transcripts was associated with the expression of TNFα, NF-κB p50, IL-4, and intratumoral inflammation in breast cancer." (PMID 29315254, 2018). "IL-4 reduces growth and metastasis of breast cancer cells acting on tumor associated myeloid cells." (PMID 29445154, 2018). "A study by Gooch, Christy, and Yee (2002) demonstrated that reduced STAT4 activation compromises the ability of IL-4 to induce apoptosis in breast cancer cells, thus favoring the survival and progression of malignant cells." (PMID 40733498, 2025). "The circular RNA circWWC3 can increase IL-4 expression and secretion in breast cancer cells, which further enhances the expression of PD-L1 and facilitates breast cancer immune evasion." (PMID 40176810, 2025). "In a study on mice, ATR exposure affects 4T1 breast cancer development, and one of the findings was that IL-4 was increased in the serum and tumor microenvironment." (PMID 40025135, 2025). "Type II IL4R is expressed on epithelial cancer cells, including breast cancer, responds to stimulation by either IL4 or IL13, and its elevated expression is associated with breast cancer metastasis." (PMID 40663259, 2025). "It has been found that CSC/TIC secretes more cytokines such as TGF-β (transforming growth factor beta; in breast cancer and glioblastoma) or IL-4 (in colon cancer) than cancer cells reducing the immune response and escalating drug resistance." (PMID 39980072, 2025). "Patients with breast cancer have been found to have significantly lower levels of circulating IL-2 and increased levels of circulating IL-4 when compared to healthy controls." (PMID 41150099, 2025). "Despite the role of IL-4/IL-4R in breast cancer progression in human and mouse models, we detected down-regulation of IL-4 in both 4T1 and MC4-L2 tumors." (PMID 39877637, 2025). "However, other studies in early-stage breast cancer have found that impaired cognition is linked to elevated cytokine levels, including IL-4, which may reflect differences in disease stage or timing of sample collection, factors known to influence cytokine profiles." (PMID 41155372, 2025).
breast carcinoma (continued). "An intriguing aspect of this analysis is the pairwise error analysis which reveals the elevated potential for IL-2 versus IL-4 signal misidentification in CD4 + T cells in breast cancer patients." (PMID 41166390, 2025). "It has been shown that blocking autocrine and paracrine IL-4 signalling impairs breast cancer stem-like cell proliferation, invasion, and tumor growth by downregulating MAPK pathway activity through up-regulation of DUSP4." (PMID 41029387, 2025). "The IL4/IL4Rα signaling axis enhances glucose and glutamine metabolism in breast cancer cells, thereby promoting tumor growth." (PMID 40656893, 2025). "Studies in breast cancer models revealed that these CD4 + T cells accelerate tumor development through secretion of IL-4 and IL-13." (PMID 38557942, 2024). "In a preclinical breast cancer model, IL-4 has been shown to activate monocytes and tumor-associated macrophages (TAM), facilitating breast cancer metastasis to the lung." (PMID 39456897, 2024). "Consistent with our findings, IL-4 is also identified to exert an inhibitory influence on the proliferation of renal, colon, and breast cancer cells." (PMID 38464838, 2024). "Overall, the mechanisms by which IL4 signaling drives the proliferation of breast cancer cells align well with those observed in other cell types." (PMID 38731867, 2024). "We have also previously shown using pharmacological inhibitors that glutaminolysis in addition to glycolysis are tied to IL4-induced proliferation in breast cancer." (PMID 38731867, 2024). "ERK1/2 pathway was related to M2 macrophage polarization induced by lactate in breast cancer, its role in M2 polarization was also been observed in IL-4-stimulated BM-derived macrophages." (PMID 38822362, 2024). "Here, we demonstrate that IL4 signaling acting on breast cancer cells through the type II receptor is mitogenic and supports the expression of pro-survival genes." (PMID 38731867, 2024). "M2 macrophage infiltration assays indicated that PAZ@Fe-MOF treatment significantly decreased the infiltration of IL-4/IL-13-stimulated THP-1 cells (M2-like macrophages) into breast cancer tissues." (PMID 39033109, 2024). "The current data suggest that changes to glucose uptake and histone acetylation are potentially key effectors of IL4 signaling in metastatic breast cancer cells." (PMID 38731867, 2024). "allegedly changed M2-polarized macrophages into M1 macrophages by electroporating sEVs from breast cancer 4T1 cell lines with miR-33 mimics during co-culturing with IL-4-induced M2-type macrophages." (PMID 38690261, 2024). "Following differentiation, we polarized them to an M2 state by the addition of IL-4 or treating the macrophages with either normal media or tumor tissue- conditioned media (TCM) from breast cancer tissue." (PMID 38302493, 2024). "Specific IL4 target genes of relevance in breast cancer metastasis were identified by RNASeq and CUT&RUN experiments and show dependence on P300 histone acetyltransferase activity for their IL4-driven expression." (PMID 38731867, 2024). "Immune cells’ secretion of interleukin-4 (IL-4) is known to enhance the expression level of the glutamine transporter ASCT2 in breast cancer cells." (PMID 38672455, 2024). "The upregulation of IL-4 not only increased the expression of PD-L1 in breast cancer cells but also promoted the expression of PD-L1 in M2 macrophages, allowing for immune escape from breast cancer." (PMID 38523627, 2024). "treated the breast cancer 4T1 cell line with rapamycin and isolated sEVs to influence M2 macrophages produced by IL-4, repolarizing them towards M1 macrophages." (PMID 38690261, 2024). "In previous work, we identified metabolic changes, including increased glucose uptake, in breast cancer cells stimulated with IL4." (PMID 38731867, 2024). "IL-4 is an inhibitory Th2 cytokine that has been shown to promote the survival of breast cancer cells and support Tregs." (PMID 38201551, 2023).